FOXM1 (forkhead box M1)
Diseases named in the same sentence as FOXM1 in open-access papers (continued):
Sharing a sentence is not in itself a finding about the gene and the disease.
melanoma (continued). "A study has revealed that downregulation of SPAG5 suppresses the ADAM17/NOTCH1 pathway by lowering the expression of FOXM1 in malignant melanoma (MM), thereby dampening the viability, migration, invasion, and EMT of MM cells." (PMID 36118675, 2022). "Based on in vitro experiments, we found that silencing PDGFRB and FOXM1 inhibited the proliferative capacity of melanoma cells." (PMID 36467505, 2022). "This study showed that MFAP2 activates the Wnt/β-catenin signaling pathway and enhances EMT during melanoma metastasis.Forkhead box M1 (FoxM1) belongs to the forkhead box transcription factor family." (PMID 36530974, 2022). "In our study, FOXM1 was upregulated in tumor tissues compared to normal tissues, suggesting a significant correlation with melanoma." (PMID 33912448, 2021). "In contrast, mitotic markers PLK1 and FOXM1 were rapidly and consistently reduced in SkMel5 melanoma cells after RGS treatment." (PMID 34092233, 2021). "FOXM1, EXO1, KIF20A, TPX2, and CDC20 are prognosis-associated core genes of melanoma, and their high expression correlates with the low prognosis of melanoma patients and can be used as biomarkers for melanoma diagnosis, treatment, and prognosis prediction." (PMID 33912448, 2021). "FOXM1, KIF20A, TPX2, CDC20, and EXO1 are hub genes of melanoma prognostic, and their high expression is strongly associated with low prognosis in melanoma patients." (PMID 33912448, 2021). "Survival curves showed that high expression of FOXM1,\ EXO1, KIF20A, TPX2, and CDC20 in melanoma patients with 5 of the top 10 hub genes was associated with reduced overall survival (OS)." (PMID 33912448, 2021). "The data showed that circ-FOXM1 expression was markedly raised in melanoma tissues in reference to normal tissues." (PMID 32183822, 2020). "In summary, circ-FOXM1 was upregulated in melanoma, and circ-FOXM1 contributed to melanoma cell proliferation, motility, and glycolysis and repressed apoptosis by upregulating FLOT2 via targeting miR-143-3p." (PMID 32183822, 2020). "Here, we report that erastin activates the transcriptional expression of Nedd4 through FOXM1 in melanoma cells." (PMID 31974380, 2020). "In order to reveal the exact roles of circ-FOXM1 in melanoma development, si-circ-FOXM1 was transfected into A2058 and A375 cells to downregulate circ-FOXM1 expression." (PMID 32183822, 2020). "Deletion of miR-143-3p restored the impacts of circ-FOXM1 silencing on cell proliferation, metastasis, and glycolysis in melanoma." (PMID 32183822, 2020). "The analysis of circ-FOXM1 in melanoma cells (A2058 and A375) and normal human epidermal melanocytes (HEMn) indicated that circ-FOXM1 was highly expressed in A2058 and A375 cells compared to HEMn cells." (PMID 32183822, 2020). "By loss-of-function experiments, we discovered that the downregulation of circ-FOXM1 led to a marked inhibition in melanoma cell proliferation, metastasis, and glycolysis and a remarked promotion in melanoma cell apoptosis." (PMID 32183822, 2020). "Recent reports also identify FOXM1 as being overexpressed in metastatic melanoma, and its targeting led to apoptosis in animal models of melanoma and in melanoma cells in culture." (PMID 32477466, 2020). "Collectively, circ-FOXM1 silencing suppressed melanoma cell progression via regulating cell proliferation, apoptosis, invasion, and glycolysis." (PMID 32183822, 2020). "All these data unraveled that circ-FOXM1 knockdown decelerated melanoma progression by sponging miR-143-3p." (PMID 32183822, 2020). "Very recently, Pin1 was reported to stimulate FoxM1 activity in metastatic melanomas and chemo-resistant cervical cell lines." (PMID 30321399, 2019). "Collectively, these results support a model where an NFATc2/c-Myc/FOXM1/EZH2 axis regulates the EMT-like/invasive program of melanoma cells." (PMID 30710146, 2019).
melanoma (continued). "In melanoma, FOXM1 mediates AURKA transcriptional activation and expression, and activation of the mitogen-activated protein kinase/ERK pathway drives AURKA expression." (PMID 31334127, 2019). "In agreement, targeting of FOXM1 and of EZH2, as well as of the upstream regulator c-Myc, induced a reversal of the EMT-like profile of melanoma cells, associated with upregulation of MITF and inhibited melanoma migratory and invasive activity." (PMID 30710146, 2019). "Here, we show that the pro-proliferative transcription factor FOXM1 is elevated and activated in malignant melanoma." (PMID 26279295, 2016). "Co-expression analysis of two independent melanoma data sets revealed several potential enzymatic regulators of FOXM1." (PMID 26279295, 2016). "To determine the role of endogenous Pin1-FOXM1 signaling in melanoma cells, we first depleted FOXM1." (PMID 26279295, 2016). "We performed MEK siRNA and PI3K/AKT inhibitor studies and FOXM1 siRNA studies in melanoma cell lines." (PMID 26640950, 2015). "The metastatic melanoma samples exhibited significantly higher expression levels of FOXM1 compared to the primary melanoma samples when the expression was normalized to GAPDH (p = 0.004)." (PMID 26640950, 2015). "In future clinical trials, the use of multiple antigen-targeted immunotherapies, including FOXM1, should be also considered in melanoma." (PMID 26640950, 2015). "In this study, we aimed to determine expression of FOXM1 in human melanoma samples and to evaluate the relationship between the FOXM1 expression and the clinical features of melanoma patients." (PMID 26640950, 2015). "We have focused our attention on Forkhead box M1 (FOXM1) as a target for anti-cancer immunotherapy in melanoma." (PMID 26640950, 2015). "We observed that both FOXM1 mRNA and protein levels were decreased when FOXM1-specific siRNA was transfected into the melanoma cells." (PMID 26640950, 2015). "We therefore conducted an immunohistochemical analysis to confirm the correlation between the expression levels of FOXM1 and the BRAF mutation status and/or the pAKT status in melanoma tissue specimens." (PMID 26640950, 2015). "All of the malignant melanoma cell lines and NHEMs exhibited comparable expression levels of FOXM1 to the PANC1 cells." (PMID 26640950, 2015). "The melanoma samples therefore exhibited significantly higher positivity for FOXM1 than the melanocytic nevus samples (p = 0.0009)." (PMID 26640950, 2015). "We found that FOXM1 was expressed in all of the melanoma cell lines, and was expressed in 49% of primary melanomas, 67% of metastatic melanomas and 10% of nevi by performing immunohistochemical staining." (PMID 26640950, 2015). "We divided the patients into two groups based on the FOXM1 expression in the primary melanoma, as determined by immunohistochemical staining." (PMID 26640950, 2015). "We showed that the inactivation of AKT by PI3K and AKT inhibitors decreased the expression levels of FOXM1 in melanoma cell lines." (PMID 26640950, 2015). "Downregulation of FOXM1 by siRNA significantly inhibited the proliferation of melanoma cells, and blockade of the MAPK and PI3K/AKT pathways decreased the FOXM1 expression in melanoma cell lines." (PMID 26640950, 2015). "have demonstrated that CDK4/6-dependent activation of the FOXM1 transcription factor suppressed senescence by an activation of critical G1/S genes promoting S phase entry in melanoma cells." (PMID 25684390, 2015). "Patients whose primary melanoma expressed FOXM1 had a significantly poorer overall survival compared to patients without FOXM1 expression (p = 0.024)." (PMID 26640950, 2015). "FOXM1 was highly expressed in the melanoma samples; however, low-level expression was observed in the melanocytic nevus samples." (PMID 26640950, 2015). "And we found that the downregulation of FOXM1 expression significantly inhibited melanoma cell proliferation." (PMID 26640950, 2015).
melanoma (continued). "In the immunohistochemical analyses, FOXM1 was overexpressed in 49% of the primary melanomas and 67% of the metastatic melanomas, whereas a markedly lower rate of expression was observed in the benign melanocytic nevi." (PMID 26640950, 2015). "We observed that the expression of miR-370 in NHEM3, which expressed low protein levels of FOXM1, was higher than that in the other NHEMs and in all of the melanoma cell lines." (PMID 26640950, 2015). "Several studies have previously reported that FOXM1 is overexpressed in human melanoma cell lines, however, to the best of our knowledge there have been no previous studies in human melanoma tissue samples." (PMID 26640950, 2015). "The patients whose primary melanoma expressed FOXM1 had a significantly poorer overall survival compared to patients without FOXM1 expression (p = 0.024)." (PMID 26640950, 2015). "Collectively, these findings suggest that lasalocid may impede melanoma cell proliferation by downregulating FOXM1 via modulation of the PI3K/AKT signaling pathway." (PMID 39781349, 2025). "The high-level expression of FOXM1 has been validated in various cancer types including melanoma." (PMID 40864319, 2025). "For eraser genes, studies have found that knocking down FTO in mouse models could increase the tumor’s sensitivity to PD-1 therapy, while ALKBH5 promoted melanoma cell proliferation, migration, and invasion by acting on FOXM1 and ABCA1." (PMID 41301778, 2025). "Collectively, these findings suggested that the transcription factor FOXM1 may exert a pivotal role in mediating the impact of lasalocid on melanoma cell proliferation and migration." (PMID 39781349, 2025). "Lasalocid markedly restrained FOXM1 expression at both mRNA and protein levels in melanoma cells." (PMID 39781349, 2025). "In melanoma cells, the FOXM1 could inhibit ferroptosis via regulating the expression of Nedd4 and the degradation of VDAC2/3." (PMID 38382091, 2024). "It has been suggested that the combined inhibition of AURKA and FOXM1 could be considered a good strategy for patients with melanoma who are refractory to the combined use of BRAF/MEK inhibitors." (PMID 37259298, 2023). "Since overexpression of FOXM1 has been reported in melanoma, compounds that are able to inhibit FOXM1 and its target genes may be valuable as anticancer agents." (PMID 37259298, 2023). "The results suggested that CDK1 and FOXM1 may serve as favorable predictive factors for melanoma patient survival." (PMID 35906389, 2022). "Besides, AURKA and FOXM1 inhibition by either genetic knockdown or pharmacologic inhibitors impair melanoma growth and survival." (PMID 35039475, 2022). "In our present study, we found that FOXM1 expression was not significantly different between metastatic melanoma tissues and primary melanoma tissues, and FOXM1 seemed not to be a potential metastasis-associated biomarker for melanoma." (PMID 35906389, 2022). "In this study, we aimed to reveal the role of SPAG5 in melanoma and clarify whether FOXM1 (forkhead box protein M1) /ADAM17 (A disintegrin and metalloproteinase 17) /NOTCH1 signaling was involved." (PMID 35138218, 2022). "FOXM1 expression level is elevated and activated in malignant melanoma." (PMID 36467505, 2022). "In summary, 294 DEGs between the primary and metastatic skin cutaneous melanoma samples were screened, and four hub genes, CDK1, FOXM1, KIF11, and RFC4, were identified that may be associated with the metastasis of melanoma." (PMID 35906389, 2022). "The purpose of this study is to explore the exact roles and mechanisms of circ-FOXM1 in melanoma." (PMID 32183822, 2020). "The outcomes illustrated that circ-FOXM1 acted as an oncogene in melanoma." (PMID 32183822, 2020). "To explore the potential mechanism of circ-FOXM1 in melanoma progression, we searched online website starBase v2.0 and found that circ-FOXM1 contained the complementary sequences of miR-143-3p, indicating that miR-143-3p might be a target of circ-FOXM1." (PMID 32183822, 2020).
melanoma (continued). "Additionally, miR-143-3p was found to be weakly expressed in melanoma and served as a target of circ-FOXM1." (PMID 32183822, 2020). "Circ-FOXM1 facilitated the development of melanoma by upregulating FLOT2 through miR-143-3p." (PMID 32183822, 2020). "miRNA 507 and lncRNA UCA1 cooperatively regulate FOXM1 expression in melanoma cells." (PMID 33680951, 2020). "Circ-FOXM1 was elevated and miR-143-3p was reduced in melanoma tissues and cells." (PMID 32183822, 2020). "In this study, we aimed to investigate the roles and mechanisms of circ-FOXM1 in melanoma." (PMID 32183822, 2020). "The results implied that the levels of glucose consumption, lactate production, HK2, and PKM2 were all repressed in A2058 and A375 cells by circ-FOXM1 downregulation compared to control groups, indicating that circ-FOXM1 knockdown repressed glycolysis in melanoma cells." (PMID 32183822, 2020). "We further validated that FOXM1-Nedd4-VDAC2/3 pathway regulated ferroptosis in melanoma cells." (PMID 31974380, 2020). "We observed that circ-FOXM1 was obviously elevated in melanoma tissues and cells." (PMID 32183822, 2020). "Moreover, there was an inverse correlation between the expression of circ-FOXM1 and miR-143-3p in melanoma tissues, as illustrated by Spearman’s correlation coefficient analysis." (PMID 32183822, 2020). "Subsequently, we divided A2058 and A375 cells into 5 groups (control, si-NC, si-circ-FOXM1, si-circ-FOXM1 + anti-miR-NC, and si-circ-FOXM1 + anti-miR-143-3p) to explore whether circ-FOXM1 could alter melanoma cell progression via targeting miR-143-3p." (PMID 32183822, 2020). "In the paper, we elucidated the effects of circ-FOXM1 in melanoma." (PMID 32183822, 2020). "First, we analyzed whether the increase in FOXM1 expression in melanomas could be due to gene amplification." (PMID 26279295, 2016). "It is tempting to speculate that FOXM1 inhibition might be beneficial to cancers other than melanoma." (PMID 26279295, 2016). "FOXM1 is not only elevated in melanoma, but also in other types of cancer." (PMID 26279295, 2016). "Thus, Pin1 correlates both with FOXM1 expression itself and FOXM1 activity in melanoma and high Pin1-FOXM1 levels suggest a poor prognosis." (PMID 26279295, 2016). "To determine whether the increased mRNA levels result in increased protein expression, we stained samples from a BRAFV600E-inducible mouse model that spontaneously develops melanomas, for Pin1 and FOXM1." (PMID 26279295, 2016). "Importantly, CENPF expression was elevated in the same area, indicating that in the Pin1-positive melanoma FOXM1 signaling is active." (PMID 26279295, 2016). "The Pin1-FOXM1 inhibitory peptides we designed in this study do show inhibitory potential toward FOXM1 activity and strongly repress tumor growth in a human melanoma ex vivo and 3D-cultured melanoids, complimentary to PLX4032 and as single entities." (PMID 26279295, 2016). "The melanoma cells positive for FOXM1 displayed homogenous cytoplasmic staining." (PMID 26640950, 2015). "Metastatic melanoma samples exhibited significantly higher mRNA levels of FOXM1 (p = 0.004)." (PMID 26640950, 2015). "Primary melanomas thicker than 2 mm were also more likely to express FOXM1." (PMID 26640950, 2015). "We found that FOXM1c is the primary FOXM1 isoform in human melanoma cell lines and NHEMs." (PMID 26640950, 2015). "Furthermore, we added a semi-qRT-PCR analysis of FOXM1 to examine the expression of FOXM1 isoforms in the melanoma cell lines and NHEMs." (PMID 26640950, 2015). "As 49% of the primary malignant melanomas and 67% of the metastatic melanomas evaluated in this study expressed FOXM1, it would be inappropriate for all patients with melanoma to be treated with FOXM1-targeted immunotherapy." (PMID 26640950, 2015). "FOXM1 has been shown to have cross-talk with the MAPK pathway in malignant melanoma." (PMID 26640950, 2015).
melanoma (continued). "Twenty-one of the 43 primary melanomas (49%) and eight of the 12 metastatic melanomas (67%) were positive for FOXM1, 55% of the positive cases showed 75–100% staining of the melanoma cells, followed by 21% of cases showing 1–24%, 17% of cases showing 25–49% and 7% of cases showing 50–74%." (PMID 26640950, 2015). "Furthermore, we found that the downregulation of FOXM1 by FOXM1-specific siRNA inhibited the proliferation of melanoma cells in vitro." (PMID 26640950, 2015). "In conclusion, FOXM1 is considered to be a new therapeutic target for melanoma." (PMID 26640950, 2015). "Perhaps, the methodologies used in this preclinical study of NRAS mutant melanoma may be used to evalute a strategy of vicarious RAS targeting to treat sarcomas with elevated Foxm1." (PMID 24216705, 2013). "In addition, we showed that Siomycin A and another similar thiazole antibiotic, thiostrepton, which has already been approved by the FDA for animal use, inhibit FoxM1 and induce apoptosis in melanoma cells." (PMID 19440351, 2009). "Since we already reported that Siomycin A and thiostrepton target FoxM1, inhibit cell growth and induce apoptosis in melanoma cells, these data further confirm that thiazole antibiotics may affect a wide variety of human cancer cells." (PMID 19440351, 2009). "We conjectured that SPAG5 may also modulate FOXM1 expression in melanoma." (PMID 35138218, 2022). "Furthermore, whether circ-FOXM1 regulated the glycolysis of melanoma cells was explored via detecting the levels of glucose consumption, lactate production, and glycolysis key enzymes (including HK2 and PKM2)." (PMID 32183822, 2020). "Silencing of c-Myc by siRNA in three different melanoma cell lines, or treatment of melanoma cells with the c-Myc inhibitor 10058-F4 downregulated FOXM1, EZH2, and H3K27me3, as well as the EMT-related markers ZEB1, N- Cadherin, α-catulin and SNAIL, but upregulated E-Cadherin." (PMID 30710146, 2019). "Therefore, further studies with a larger sample number are needed in order to confirm whether FOXM1 is a new therapeutic target for melanoma." (PMID 26640950, 2015). "Together, these findings suggest lasalocid down-regulates FOXM1 by inhibiting PI3K/AKT, impeding melanoma cell proliferation." (PMID 39781349, 2025). "The results suggested that melanoma patients with high expression of CDK and FOXM1 had shorter OS (CDK1: OS P = 0.047; FOXM1: OS P = 0.00043)." (PMID 35906389, 2022). "The protein expression of FOXM1, KIF20A, TPX2, CDC20, and EXO1 was higher in melanoma than in paraneoplastic tissues, consistent with our analysis results." (PMID 33912448, 2021). "In melanomas, Interaction between UCA1 and miR-507 inhibit FOXM1 protein degradation to enhance cell proliferation, invasion, and G0/G1 cell cycle arrest." (PMID 33204264, 2020). "Collectively, these findings suggest that FOXM1 inhibits ferroptosis by regulating Nedd4 expression and subsequent VDAC2/3 degradation in melanoma cells." (PMID 31974380, 2020). "In the presented research, the expression patterns of circ-FOXM1, miR-143-3p, and FLOT2 in melanoma were determined." (PMID 32183822, 2020). "NFATc2 silencing by shRNA or treatment of melanoma cells with inhibitors of NFATc2 (AM404), c-Myc (10058-F4), FOXM1 (Siomycin A) or EZH2 (GSK126) reduced significantly migratory activity, by wound healing assay, and invasive ability." (PMID 30710146, 2019). "Here we show that the EMT-like transcriptional program of melanoma cells is indeed controlled by NFATc2 acting on c-Myc, FOXM1 and EZH2 and that NFATc2 regulates melanoma migratory and invasive activity in vitro, and tumor growth in vivo." (PMID 30710146, 2019). "As a result, FOXM1, a target of miR-507, is downregulated upon UCA1 depletion in melanoma cell lines, resulting in the inhibition of cell proliferation." (PMID 28415644, 2017). "Here, we showed that many human melanomas express elevated levels of the pro-proliferative and pro-survival MEK-target FOXM1." (PMID 26279295, 2016).